ABHD1 (abhydrolase domain containing 1)
Synonyms: LABH1; FLJ36128
Tractability: Antibody: UniProt predicts a signal peptide or a membrane-spanning region. PROTAC: its protein half-life has been measured.
Gene: Protein-coding gene on chromosome 2 (27,123,789 to 27,130,812, forward strand). Ensembl gene ENSG00000143994.
Subcellular location: Membrane
Gene Ontology:
Molecular function: protein binding; acetylesterase activity; monoacylglycerol lipase activity
Biological process: medium-chain fatty acid biosynthetic process; medium-chain fatty acid catabolic process
Cellular component: membrane
Genetic constraint (gnomAD): Loss-of-function variants: 47 observed, 44.1 expected, observed/expected ratio (o/e) 1.07, 90% interval 0.84 to 1.36. The upper end of that interval is the gene's LOEUF score, 1.36, which puts it in group 5 of 6, group 1 being the genes least tolerant of losing a copy. Missense variants: 550 observed, 529.94 expected, observed/expected ratio (o/e) 1.04, 90% interval 0.97 to 1.11. Synonymous variants: 205 observed, 215.06 expected, observed/expected ratio (o/e) 0.95, 90% interval 0.85 to 1.07.
Homologues: Orthologues: chimpanzee ABHD1 (98% identical), macaque ABHD1 (94% identical), rat Abhd1 (80% identical), rabbit ABHD1 (79% identical), dog ABHD1 (78% identical), pig ABHD1 (75% identical), guinea pig ABHD1 (75% identical), mouse Abhd1 (52% identical), tropical clawed frog ABHD1 (48% identical), Drosophila melanogaster Hydr1 (39% identical), Caenorhabditis elegans abhd-3.1 (30% identical), Caenorhabditis elegans abhd-3.2 (30% identical). Paralogues in human: ABHD3 (44% identical), ABHD15 (25% identical), ABHD2 (22% identical).
Diseases named in the same sentence as ABHD1 in open-access papers:
ABHD1 is named in the same sentence as 11 diseases in open-access papers, as found by Europe PMC text mining. Sharing a sentence is not in itself a finding about the gene and the disease. The quoted sentences say what the papers report.
diabetes (1 paper, 2024). "In consideration of the role of ABHD1 in lipid metabolism, deeper exploration of how ABHD1 regulates lipid metabolism disorders especially in diabetes status will extend in the future." (PMID 39619568, 2024). "Although studies of ABHD1 in diabetes and its complications are rare, research has found that inhibitors of ABHD6 in the same family may play a role in the treatment of type 2 diabetes, insulin resistance, and metabolic syndrome by promoting insulin secretion." (PMID 39619568, 2024).
dyslipidemia (1 paper, 2024). "Intriguingly, in consideration that ABHD1 has compact correlation with dyslipidemia, inflammation response, and oxidative stress, whether ABHD1 acts as a latent pathogenic factor in DR had drawn our attention." (PMID 39619568, 2024).
endometriosis (1 paper, 2025). The growth of functional endometrial tissue in anatomic sites outside the uterine body. "Through this analysis, we identified 42 genome-wide significant (5 × 10−8) genetic variants significantly associated with endometriosis, 6 of which were not reported previously: ABHD1/2p23.3, TMEM131/2q11.2, XRCC4/5q14.2, PPP1R9A/7q21.3, XKR6/8p23.1, and TRPS1/8p23.3." (PMID 40262193, 2025).
Hypertension (1 paper, 2024). The presence of chronic increased pressure in the systemic arterial system. "In renal cell lines, overexpression of ABHD1 is related with ROS production, and in oxidative stress–induced hypertension mouse model, kidney ABHD1 expression significantly ascends." (PMID 39619568, 2024).
ABHD1 also shares sentences with these, for which no sentence is quoted: diabetic retinopathy (1 paper); endothelial dysfunction (1); Hirschsprung disease (1); Hyperglycemia (1); Insulin resistance (1); lipid metabolism disorders (1); type 2 diabetes (1).